CGAS (cyclic GMP-AMP synthase)
Diseases named in the same sentence as CGAS in open-access papers (continued):
Sharing a sentence is not in itself a finding about the gene and the disease.
tumor (continued). "Notably, as a cGAS agonist, Mn2+ has been demonstrated to be powerful anti-tumor agents by promoting the proliferation of CD8+ T cells and natural killer cells, as well as the maturation and antigen presentation of dendritic cells, in a cGAS-dependent manner." (PMID 35536585, 2022). "Importantly, the cGAS-STING pathway also leads to cross-talk between tumor and immune cells, with antigen-presenting cells (APC) sensing tumor-derived cGAMP or damaged DNA that further enhances the STING-dependent antitumor immunity." (PMID 36559204, 2022). "MiR-25/93 are hypoxia-responsive miRNAs that could repress NCOA3 and impair cyclic-GMP-AMP synthase (cGAS)-mediated anti-tumor immunity in BC." (PMID 35499045, 2022). "Similarly, TREX1 can degrade DNA derived from micronuclei in chromosomally unstable tumor cells and prevent activation of cGAS/STING." (PMID 35602594, 2022). "Moreover, cGAS-STING-dependent DNA-sensing of micronuclei in tumor cells can couple chromosome instability to tumor metastasis, suggesting a contradictory role for the pathway in cancer biology." (PMID 35983076, 2022). "In the tumor microenvironment, double stranded DNA (dsDNA) in tumor cell debris is phagocytosed by dendritic cells and macrophages and transferred to the cytosol where it activates the cGAS-STING pathway." (PMID 35911757, 2022). "Notably, loss of cGAS-mediated AIS via inhibitor pretreatment also decreased the regression of local tumours, suggesting a role of cGAS-mediated AIS in the local effect." (PMID 36402783, 2022). "We further find that activating mitotic SENP3 by mutating the phosphorylation sites increases the formation of micronuclei, which enhance cGAS signaling-dependent innate immune response in tumor cells followed by stimulating host CD8+ T cell-mediated anti-tumor immunity in C57BL/6 mice." (PMID 35869062, 2022). "However, CpG/αOX40 has been proven to have excellent anti-tumor effects, which can promote the release of dsDNA and induce the generation of endogenous cGAMP, thereby indirectly activate the cGAS-STING pathway." (PMID 35748951, 2022). "For example, in dendritic cells present in the necrotic core of tumors, the cytosolic dsDNA receptor cyclic GMP-AMP synthase (cGAS) is activated by tumor cell-derived dsDNA which leads to stimulator of interferon genes (STING)-dependent inflammatory signalling." (PMID 35911757, 2022). "On the other hand, a minimal concentration threshold of tumor-derived dsDNA is required for efficient dsDNA sensing and may kinetically impede cGAS-STING activation in DCs22." (PMID 36167857, 2022). "The cGAS-STING pathway is essential for anti-tumour T cell responses." (PMID 36106115, 2022). "And the loss of cGAS-mediated AIS decreased the regression of local and abscopal tumours." (PMID 36402783, 2022). "Although we have no direct evidence to support for the micronuclei as essential for mitotic SENP3-activated innate immune response, we identify cGAS as an essential regulator for the mitotic SENP3-activated innate immune response in tumor cells via promoting micronucleus formation." (PMID 35869062, 2022). "The comparative analysis of DC activity after conditioning with tumor cell debris or co-incubation with tumor cells also confirmed that the cGAS-STING activation in DCs was caused by the tumor-derived dsDNA rather than those membrane-bound antigens." (PMID 36167857, 2022). "However, the efficacy of ICBs was substantially increased in tumor models when combined with either the cGAS product, cGAMP, or a synthetic cGAMP analog in cGAS-STING signal sufficient context." (PMID 35292881, 2022). "This combinatory activity may amplify the effect of cytosolic DNA on activating cGAS-STING-type I IFN signaling to potentiate anti-tumor immunity." (PMID 36230769, 2022). "Emerging evidence has shown the importance of the cGAS-STING pathway in tumor immunotherapy 36,37." (PMID 34158843, 2021).
tumor (continued). "As cancer cells often have unstable nuclei with excess genomic DNA leaked into the cytoplasm, thereby activating cGAS to produce 2′3′-cGAMP, this might be a natural route to enhance immune targeting of tumours." (PMID 34905701, 2021). "Among the studies on the relationship between the cGAS–STING pathway and tumors, it was surprising that researchers found that the cGAS–STING pathway might be relevant to some tumor metastasis." (PMID 34906241, 2021). "Taken together, cGAS promoted tumor growth by regulating DNA replication in vivo and vitro." (PMID 37305397, 2021). "Furthermore, knockdown of cGAS significantly decreased tumor mass and growth rate in BALB/c-nude mice, meanwhile, H&E staining of tissues confirmed the tumors were induced by the injected GC cells." (PMID 37305397, 2021). "In addition to T lymphocytes, the anti-tumor effect of the activated cGAS-STING signal pathway is also closely related to TAMs." (PMID 34956229, 2021). "The intensity of inflammation and the extent of cGAS/STING activation should be the critical factors in determining whether this pathway is antitumor or pro-tumor." (PMID 35265630, 2021). "Moreover, the cGAS/STING pathway can also support metastasis by promoting a welcoming tumor microenvironment." (PMID 35008251, 2021). "In addition to tumor cells that can specifically activate the cGAS-STING pathway, some antigen-presenting cells (APCs), such as DCs and macrophages, can also initiate the body’s anti-tumor response via this pathway." (PMID 35046953, 2021). "Before that, we have summarized that Mn2+ could serve as an effective drug to produce anti-tumor immune responses via activating the cGAS-STING signal pathway dependent on dsDNA." (PMID 34956229, 2021). "As the activation of the cGAS/STING pathway in the tumor microenvironment can induce the effective cross-priming of tumor-specific antigens and promote the infiltration of effector T cells, STING agonists have been developed to simulate this activation in order to enhance the anticancer effect." (PMID 35046953, 2021). "In TME, mtDNA of tumor cells were ingested by DCs and activate cGAS to increase IFN-I production in DC cytoplasm; inhibition of CD47 could suppress mtDNA degradation by phagosomes, which contributes to enhance antitumor adaptive immunity." (PMID 35265630, 2021). "cGAS is a key modulator of the innate immune response that can influence the tumor microenvironment in ways that may be detrimental or beneficial." (PMID 34308492, 2021). "In addition, relevant studies have also found that activation of the cGAS-STING signal pathway has a positive effect on tumor growth, proliferation, and metastasis." (PMID 34956229, 2021). "So researchers speculated that Mn2+ might act as an effective agonist/drug to produce anti-tumor immune responses via activating the cGAS-STING signal pathway." (PMID 34956229, 2021). "RNF111 was considered to have tumor suppressive activity, our study implied that it might partially be attributable to its neddylation modification of cGAS to facilitate immune responses." (PMID 33720974, 2021). "However, recent studies have shown that the cGAS/STING pathway can also be kidnaped by tumor cells to favor tumor progression in metastatic sites." (PMID 35008251, 2021). "Whether these mechanisms are initiated in irradiated GBM remains unknown, but current data suggests that activation CGAS-STING in myeloid cells is important for anti-tumor immunity against this tumor type." (PMID 34094969, 2021). "Several recent studies have linked cGAS–STING signaling to control of cellular senescence as well as the senescence associate secretory phenotype (SASP) that is responsible for a pro-inflammatory phenotype with both pro and anti-tumor effects." (PMID 34884568, 2021).
tumor (continued). "Recent studies have found that the cGAS-STING pathway being activated in the setting of genome instability can be attributed to dMMR 38, PARP inhibitor treatment, or functional loss of BRCA1/2 genes 39, and it predicts a better prognosis of tumor patients." (PMID 34158843, 2021). "The cGAS‒STING signaling pathway mediates the innate immune response to restrict infections caused by various pathogenic microorganisms containing DNA and detects tumor-derived DNA to induce antitumor immune responses." (PMID 34718659, 2021). "As expected, restoring cGAS expression recovered the anti-tumor immune response." (PMID 35265630, 2021). "Recently, studies revealed that the cGAS-STING pathway is closely related to tumor immunity." (PMID 33843442, 2021). "Moreover, STING can also regulate cell cycle in a cGAS-STING axis-independent manner in some tumor models." (PMID 35046953, 2021). "We recently reported that cGAS suppresses HR repair in the nucleus, therefore we hypothesize that cGAS nuclear translocation enhances DNA damage in GC tumor cells, which could explain their increased radiation sensitivity." (PMID 37305397, 2021). "Other studies have also found that the cGAS-STING signal pathway could regulate CD8+ T cells differentiation to produce anti-tumor responses, including hepatocellular carcinoma, breast cancer, melanoma, colon cancer, and lung cancer." (PMID 34956229, 2021). "It would therefore be interesting to determine if these regulatory mechanisms are upregulated following tumor ablation and whether stimulation of the cGAS/STING pathway upon ablation would be beneficial to achieve an in situ cancer vaccine." (PMID 33936033, 2021). "Interestingly, there has been suggestion of an interplay between stromal (or microenvironmental) and tumor cGAS–STING signaling with regard to regulating the immune-based anti-tumor response to DNA-damaging therapies." (PMID 34884568, 2021). "Preclinical research has shown that activation of the cGAS/STING pathway after DNA damage enhances immune cell infiltration into the tumor microenvironment (TME) through secretion of pro-inflammatory type I interferon (IFN) and induction of a senescence-associated secretory phenotype (SASP)." (PMID 34204886, 2021). "TREX1 expression is initiated at a sufficient level for degrading DNA, which can accumulate in the cytosolic region of the treated tumor cell, precluding interferon (IFN-1) pathway activation induced through cyclic GMP-AMP (cGAMP) synthase (cGAs) and the associated downstream adaptor STING." (PMID 34519260, 2021). "However, there are additional studies that indicate IFN-production in vitro is unaffected by cGAS-knockout in DCs, but is attenuated by cGAS-knockout in tumor cells, by STING-knockout in DCs, or by connexin 43-knockout in tumor cells." (PMID 33868310, 2021). "Chromosomal instability caused micronuclei damage and induced the production of cytoplasmic dsDNA, which could effectively activate the cGAS-STING signal pathway to promote tumor metastasis." (PMID 34956229, 2021). "However, tumor rejection was further boosted by intratumoral injection of cGAMP suggesting that endogenous cGAS agonists fail to fully activate STING in TRAMP-C2 cells." (PMID 33790360, 2021). "Similarly, many other studies have also found CD8+ T cells-dependent anti-tumor responses are mediated by the cGAS-STING signal pathway." (PMID 34956229, 2021). "Additionally, in the cytoplasmic compartment of immune cells, tumor DNA binds cyclic GMP-AMP synthase (cGAS) and acts in conjunction with Stimulator of Interferon Genes (STING) signaling to initiate IFNI production." (PMID 33801234, 2021). "Finally, in tumors with homologous recombination repair defects, PARP inhibitors are also capable of augmenting PD-1/PD-L1 inhibitors through enhancing tumor immunogenicity and cGAS/STING signaling activity." (PMID 34572908, 2021).
tumor (continued). "However, chromosome instability enhances tumor metastasis through the rupture spills genomic DNA from micronuclei that in turn, activates cGAS-STING pathway." (PMID 34207286, 2021). "Moreover, the genomic instability of tumor cells is another considerable element in cGAS/STING pathway-related pro-tumor and metastasis." (PMID 35265630, 2021). "The previous results demonstrated that TAMs played a necessary role in the recruitment and differentiation of T cells, which might be one of the mechanisms by which the cGAS-STING signal pathway exerted powerful anti-tumor effects." (PMID 34956229, 2021). "However, current studies propose the potential use of the cGAS/STING pathway in tumor initiation and metastasis." (PMID 35265630, 2021). "Nevertheless, dying tumor cells still release dsDNA (and/or 2’3’ cGAMP, its cGAS catalyzed product) into the TME, which may result in the activation of STING+ cells in the tumor stroma, including DC and VEC." (PMID 34054879, 2021). "In addition to tumor-derived DNA, the tumor mitochondrial DNA (mtDNA) can also trigger the cGAS-cGAMP-STING innate immune response." (PMID 34512146, 2021). "In early preneoplastic cells, the cGAS-STING pathway acts as a tumor suppressor." (PMID 35046953, 2021). "Meanwhile, the cytoplasmic dsDNA induced by chromosomal instability could promote tumor metastasis in a manner dependent on the cGAS-STING signal pathway of tumor cells." (PMID 34956229, 2021). "When immune checkpoint inhibitors silence inhibitory signals for T cell activation and activate an effective antitumor response, accumulation of self-DNA released from dying tumor cells triggers the cGAS-STING pathway to induce the production of interferons and inflammatory cytokines." (PMID 34925345, 2021). "In the recent issue of Cancer Cell, Lu and Guan demonstrated that activation of the cGAS‐STING pathway in tumor tissues was significantly and positively correlated with the prognosis of patients bearing dMMR tumors but not that of patients with pMMR (proficient MMR) tumors." (PMID 34047476, 2021). "Indeed, at doses higher than 12 Gy, cytosolic dsDNA is cleared by three prime repair exonuclease 1 (TREX1), precluding the activation of the cGAS pathway to induce type I interferon, and abolishing the radiotherapy-induced anti-tumor immune response." (PMID 34386508, 2021). "An important function of cGAS-STING signaling pathway activation is to recruit tumor-specific immune cells via DCs, and thus we have reason to believe that combining cGAS-STING signaling pathway activators with PD-1/PD-L1 specific blockade will certainly greatly improve the efficacy." (PMID 34483930, 2021). "In addition, TREX1 inhibits the transfer of dsDNA from irradiated tumor cells to dendritic cells (DCs) via tumor-derived exosomes, resulting in dampened cGAS/STING activation and IFN-β production in DCs." (PMID 33888558, 2021). "On the other hand, prolonged activation of the cGAS pathway promotes tumor formation by causing inflammation-driven tumorigenesis and metastasis; nuclear cGAS also induces genome instability by inhibiting HRR to promote tumor development." (PMID 37305397, 2021). "As shown in other tumor types, inhibitors targeting molecules such as ATR, Wee1 and Chk1, which induce replication-associated DNA damage and potentially cGAS/STING pathway activation through subsequent cytosolic DNA fragments in HNSCC, are promising candidates for combination treatments in HNSCC." (PMID 34204886, 2021). "In addition to mediating a protective immune response to infection, the cGAS-STING pathway can also detect tumor-driven DNA and impart antitumor immunity as well as play a role in the development of various inflammatory conditions." (PMID 34925345, 2021). "The initial cGAS-stimulation resulting from undegraded DNA could be tumor-intrinsic or immune cell-intrinsic with the resulting cGAMP signaling molecule transferred to neighboring cells." (PMID 33868310, 2021).
tumor (continued). "However, both PARPi and CHK1i have synergistic effects on tumor growth when administrated in combination with anti-PD-L1 immunotherapy in mice proficient for the cGAS-STING pathway." (PMID 34249949, 2021). "However, it was found that patients with high expression of cGAS had a better response to radiotherapy, which suggests a dual function of cGAS on tumor progression and treatment response." (PMID 37305397, 2021). "Activation of type I IFN raised importance in the context of cancer as an anti-tumorigenic mechanism of the cell, leading to immunosurveillance: Detection of tumor-derived DNA by innate immune sensors and cGAS-dependent activation of STING leads to type I IFN secretion." (PMID 34381458, 2021). "Furthermore, knockdown of cGAS suppresses DNA damage and inhibits tumor growth both in vitro and in vivo, suggesting cGAS as a tumor enhancer." (PMID 33105828, 2020). "Temporary activation of cGAS-STING in innate immune cells could enhance the anti-tumor effect, whereas sustained activation of cGAS-STING might induce immune tolerance of the tumor." (PMID 32411126, 2020). "Moreover, the correlations between the expression of cGAS-STING pathway members and the marker sets of immune cells suggest the role of cGAS-STING pathway members in regulating tumor immunology in HCC." (PMID 33006365, 2020). "Furthermore, cGAS–STING signaling is activated within DCs that have internalized genetic material originating from tumor cells into the cytosol." (PMID 33238631, 2020). "The extent of the protumor effect may depend on levels of genome instability and cGAS activation in tumor cells." (PMID 32541866, 2020). "However, only STING-deficient mice showed defective tumor-specific CD8+ T cells and accelerated tumor growth, suggesting that the cGAS-STING pathway is a major pathway that spontaneously detects cancer." (PMID 32541866, 2020). "Further studies of a co-culture of tumor-immune cells revealed that a downregulated cGAS-STING pathway could induce cancer resistance to immune effectors." (PMID 32571374, 2020). "The cGAS–STING pathway performs an essential function in the mechanism of tumor metastasis." (PMID 32195086, 2020). "Thus, activation of cGAS-STING signaling by dsDNA in tumor cells alone strongly cooperated with MVNs to amplify innate immune production of specific cytokines and chemokines." (PMID 33013881, 2020). "For example, astrocytes produce plasminogen that induces apoptosis of cancer cells, whereas astrocyte-derived cyclic GMP-AMP synthase (cGAS) and microRNAs (miRNAs) delivered to tumor cells via gap junctions or exosomes have been shown to promote the formation of brain metastases." (PMID 32399646, 2020). "In addition, the same experiments using cGAS or TNF KO cells in vivo showed that either depletion deeply impaired paclitaxel tumor response." (PMID 31937780, 2020). "Therefore, STING agonists are being investigated as cancer therapeutics to activate or mimic the cGAS/STING signalling pathway for promoting immune-mediated tumour rejection." (PMID 33121210, 2020). "Thus, tumor cell cGAS-STING signaling not only produces T cell chemoattractants, but also primes tumor vasculature for immune cell escape." (PMID 33013881, 2020). "Furthermore, new evidence suggests that tumor cell-derived exosome DNA (ExoDNA) can also activate immune cells by STING/cGAS, and therefore, ExoDNA can both regulate tumor immunity and act as a key regulator of checkpoint immunotherapy." (PMID 33183286, 2020). "Combined with anti-PD-1 antibodies, the survival rates were significantly improved, suggesting that cGAS-STING ligands could improve the anti-tumor activity of other established therapeutic agents and vice versa." (PMID 32774773, 2020). "Collectively, these findings suggest that cGAS-STING signaling might act as a tumor suppressor in certain types of cancers." (PMID 32854711, 2020).